PHGDH (phosphoglycerate dehydrogenase)
Diseases named in the same sentence as PHGDH in open-access papers (continued):
Sharing a sentence is not in itself a finding about the gene and the disease.
breast carcinoma (continued). "In addition, PHGDH can be ubiquitinated by Parkin in breast cancer, thus low Parkin expression contributes to PHGDH overexpression." (PMID 38710705, 2024). "However, Parkin was identified as a negative regulator of PHGDH by interacting with it and promoting its degradation through ubiquitination in breast cancer cells." (PMID 39472438, 2024). "To corroborate the lethal effect of CBR-5884 on cells with heightened serine synthesis propensity, we examined PHGDH protein expression levels in MDA-MB-231 (a breast cancer cell line), IOSE-80 (a normal human ovarian surface epithelial cell line), and the EOC cell lines SKOV3 and ID8." (PMID 38733440, 2024). "Hence, the overexpression of PHGDH in specific breast cancer types leads to increased reliance on the serine pathway." (PMID 38945960, 2024). "In addition, a study confirmed that the PHGDH inhibitor CBR-5884 can be used not only to treat breast cancer but also to treat epithelial ovarian cancer." (PMID 38945960, 2024). "In contrast, CBR-5884 is an inhibitor of phosphoglycerate dehydrogenase, blocking de novo serine synthesis in cells, and is selectively toxic to cancer cell lines with high serine biosynthetic activity against melanoma and breast cancer lines." (PMID 38587428, 2024). "Furthermore, PHGDH has been shown to be amplified in breast cancer and multiple myeloma, further underscoring its suitability as an ideal target of serine biosynthesis." (PMID 38690164, 2024). "Breast cancer cells with a high PHGDH expression have increased serine synthesis flux." (PMID 37664062, 2023). "Moreover, the downregulation of E3 ubiquitin ligases (Parkin and RNF5), or upregulation of deubiquitinating enzyme JOSD2, has been reported as crucial mechanism for PHGDH overexpression in breast cancer or lung adenocarcinoma." (PMID 36823188, 2023). "PHGDH expression was elevated in 90% of brain metastases of breast cancer." (PMID 37046596, 2023). "The first enzyme in the de novo serine synthesis pathway (SSP)—phosphoglycerate dehydrogenase (PHGDH) is found up-regulated in melanoma and breast cancers through genomic amplification by increasing the copy number of the gene, which adequately support cancer cell growth in the absence of serine." (PMID 35178349, 2022). "Differently, breast cancers colonizing the brain, due to the low availability of serine in the cerebral tissues, need to maintain high expression of the first enzyme of the serine biosynthetic pathway phosphoglycerate dehydrogenase (PHGDH)." (PMID 35158815, 2022). "This leaves open the possibility that low PHGDH could also contribute to a serine auxotrophy phenotype in luminal breast cancer patients, and our data demonstrate that low PHGDH can induce serine auxotrophy in other types of cancer cells." (PMID 35045283, 2022). "Besides, PHGDH, an enzyme that functions in the de novo serine synthesis, is found to overexpress in human melanoma and breast cancers." (PMID 35935878, 2022). "Moreover, SF3B1 hotspot mutations on codons K700, K666 and H662 have been described to induce dysregulation of metabolic enzymes, including PHGDH, in acute myeloid leukemia and breast cancer cells, leading to increased dependency on serine." (PMID 35565242, 2022). "Interestingly, very recently it was shown that glycosylation can be modulated by the heterogeneous protein expression of the metabolic enzyme phosphoglycerate dehydrogenase (PHGDH), which affects breast cancer-derived metastasis formation." (PMID 36226054, 2022). "Similarly, increased de novo serine biosynthesis via PHGDH in breast cancer, where extracellular serine is limited, has a critical role for in vivo proliferation and for the maintenance of mitochondrial redox homeostasis, and thereby cancer stemness." (PMID 34068120, 2021). "Finally, a recent work from Vander Heiden’s lab demonstrated that increased PHGDH expression promotes tumor progression in mouse models of both melanoma and breast cancer in serine-limited tumor micro-environment." (PMID 33499022, 2021).
breast carcinoma (continued). "PHGDH knockdown caused a reduction in the number of breast CSCs in vitro and orthotopic tumors, suggesting the requirement of PHGDH for the induction of a breast CSC phenotype and promoting tumor initiation and breast cancer metastasis." (PMID 33801846, 2021). "PHGDH is also a ubiquitination substrate of RNF5 in the study of breast cancer cells." (PMID 34350460, 2021). "Significantly, PHGDH is amplified in a number of cancers, including breast cancer, melanoma, lung cancer, colon cancer, and neuroendocrine prostate cancer (NEPC), and higher PHGDH expression is associated with increased serine biosynthesis and poorer survival and prognosis." (PMID 33946927, 2021). "Importantly, this localization was found to hold in the PHGDH-low breast cancer MDA-MB-231 as well, demonstrating that the mechanism of increased localization of KICSTOR-GATOR1 to the lysosome by perhexiline is not PHGDH-dependent." (PMID 33503424, 2021). "In addition, the three enzymes constituting this pathway (phosphoglycerate dehydrogenase (PHGDH), PSAT-1, and PSPH) are overexpressed in many cancer types (breast cancer, melanoma, glioma) and often associated with poor prognosis in the patient." (PMID 31979167, 2020). "Thus, PHGDH deficiency can attenuate chemotherapy-induced BCSC enrichment and sensitize breast cancer cells to chemotherapy." (PMID 32296646, 2020). "PHGDH overexpression has been observed in 70% of estrogen receptor-negative breast cancers, and high PHGDH expression indicates elevated serine synthetic flux of breast cancer cells." (PMID 32296646, 2020). "In ER+ breast cancer, PHGDH may be a novel therapeutic target to reverse recurrence/resistance to tamoxifen therapy." (PMID 32226297, 2020). "The expression of PHGDH is quite frequently enhanced in breast carcinomas." (PMID 31847543, 2020). "PHGDH-amplified cells are dependent on expression of catalytically active enzyme to proliferate, and high PHGDH expression is associated with negative clinical outcomes in breast cancer, glioma, cervical cancer, lung cancer, and colon cancer." (PMID 31331318, 2019). "The first serine-synthetic enzyme PHGDH was reported to promote pancreatic and breast cancer." (PMID 31861486, 2019). "ER+ breast cancer cell lines are known to be more susceptible to serine depletion, probably due to lack of amplification of phosphoglycerate dehydrogenase, and thus are less addicted to serine metabolism compared with ER− tumors." (PMID 31152137, 2019). "The growth inhibition effect seen in PHGDH-amplified breast cancer cells, together with increasing evidence of the prevalence of PHGDH expression in certain cancer types, makes the design of a PHGDH inhibitor highly desirable to allow for further target validation using a chemical probe." (PMID 29568346, 2018). "Indeed, the gene encoding phosphoglycerate dehydrogenase (PHGDH), the rate-limiting enzyme of the serine biosynthesis pathway, is amplified in breast cancers and melanoma." (PMID 25250177, 2014). "It would be interesting to determine whether PKM2 activation could combine with PHGDH inhibition to have more dramatic effects on the growth of established ER- breast cancer models." (PMID 24318446, 2013). "To gain insight into whether PHGDH, the key enzyme in the glucose metabolism pathway, is necessary for breast cancer cell proliferation, we first examined the expression pattern of PHGDH in eleven human breast cancer cell lines with varying ER status." (PMID 24318446, 2013). "The results were consistent with the PHGDH expression pattern in melanoma and breast cancer." (PMID 23229761, 2013). "Next, we tested whether breast cancer cells with PHGDH overexpression were sensitive to PHGDH knockdown." (PMID 24318446, 2013). "Our findings suggest that other mechanisms or pathways may bypass exclusive dependence on PHGDH in established human breast cancer xenografts, indicating that PHGDH is dispensable for the growth and maintenance of tumors in vivo." (PMID 24318446, 2013).
breast carcinoma (continued). "Besides breast cancer, PHGDH is also amplified in human melanoma and PHGDH knockdown impairs proliferation of those melanoma cells." (PMID 24318446, 2013). "Furthermore, the presence of ECs in co-culture with breast cancer cells lowered PHGDH expression, revealing a potential EC-tumor cell crosstalk that may be modulating tumor cell metabolism and thereby increasing migratory and invasive capabilities." (PMID 39567756, 2025). "Therefore, combining PHGDH inhibitors with chemotherapy drugs may have a synergistic effect, offering a new breast cancer treatment option." (PMID 39973065, 2025). "Therefore, PHGDH may be a novel therapeutic target to reverse recurrence/resistance to tamoxifen therapy in ER+ breast cancer." (PMID 37187454, 2023). "Therefore, NCT-503 may be used as a targeted therapy for tumors, such as lung cancer, breast cancer, and other tumors that highly express PHGDH." (PMID 36699468, 2022). "In fact, it has been reported that phosphoglycerate dehydrogenase (PHGDH) expression accelerates tumor growth in mouse models of melanoma and breast cancer; however, whether this acquired fitness advantage may induce the angiogenic process by secreting serine, remains obscure." (PMID 35681715, 2022). "Moreover, elevated levels of 2HG in breast cancer cells without IDH mutation can be also driven by overexpression of the serine biosynthetic pathway enzyme phosphoglycerate dehydrogenase (PHGDH), which can catalyze the NADH-dependent reduction of αKG to 2HG." (PMID 25980580, 2015). "Therefore, targeting the serine synthesis pathway may be therapeutically valuable in breast cancers with elevated PHGDH expression or amplifications." (PMID 24318446, 2013). "The qPCR analysis of PHGDH and D2HGDH expression in tissue samples, along with TCGA database analysis, revealed that PHGDH expression was highest and D2HGDH expression was lowest in TNBC tumors compared to other breast cancer subtypes." (PMID 39910592, 2025). "S-palmitoylation of PHGDH and FASN promotes chemoresistance in breast cancer, while palmitoylation of ACACA and GPX4 influences lipid metabolic reprogramming and ferroptosis resistance, respectively." (PMID 40626019, 2025). "Consistent with our findings, several recent studies reported that high expression of NAT10, PHGDH, or PSAT1 is correlated with the poor survival in breast cancer, especially the TNBC." (PMID 40138393, 2025). "PHGDH and PSAT1 are essential enzymes for the glucose-derived serine/glycine biosynthesis pathway; using glucose, metastatic breast cancer cells synthesize serine/glycine to survive the amino acid–limited brain microenvironments." (PMID 40138393, 2025). "Its pro-tumorigenic effects manifest via serine pathway activation in colorectal and breast cancers, where ATF4 knockdown suppresses PHGDH expression and chemoresistance." (PMID 40265021, 2025). "Our study reveals a significant elevation of D-2HG levels in the serum and tumor tissues of TNBC, potentially regulated by high PHGDH expression and low D2HGDH expression, both of which correlate with poor prognosis in breast cancer." (PMID 39910592, 2025). "We further investigated the expression of NAT10, PHGDH, and PSAT1 in the AURORA US Metastasis Project (GSE193103), a larger cohort with paired breast cancer metastases and primary tumors." (PMID 40138393, 2025). "Among all main metastasis sites of breast cancer, brain metastases exhibited the highest levels of NAT10, PHGDH, and PSAT1, followed by liver metastases." (PMID 40138393, 2025). "Canonically, PHGDH has been considered the rate-limiting step of the SSP, and apart from ER/PR+ breast cancer, most instances of SSP suppression in other cell lines involved PHGDH downregulation." (PMID 40462988, 2025). "We also show that breast cancer cell growth and NAT10 downstream genes PHGDH and PSAT1 are regulated by NAT10 in an RNA helicase activity–dependent manner." (PMID 40138393, 2025).
breast carcinoma (continued). "A non‐competitive inhibitor of PHGDH, CBR‐5884, has been identified to block the de novo synthesis of serine in melanoma and breast cancer cells, being selectively toxic for cancer cells lines with high serine biosynthesis." (PMID 38115544, 2024). "For instance, heightened PHGDH overexpression increases NADPH levels, maintains mitochondrial redox homeostasis, reduces apoptosis, and fosters metastasis in breast cancer cells." (PMID 38733440, 2024). "Other PHGDH inhibitors, NCT‐502 and NCT‐503 reduce the production of glucose‐derived serine in breast cancer and suppress the growth of PHGDH‐dependent cancer cells in culture and in orthotopic xenograft tumors." (PMID 38115544, 2024). "Phosphoglycerate dehydrogenase (PHGDH), the first rate-limiting enzyme of serine synthesis, is frequently upregulated in breast cancer and promotes tumor progression." (PMID 39472438, 2024). "In fact, genomic analyses have shown that many cancers, especially breast cancer and non-small cell lung cancer (NSCLC), exhibit amplification and upregulated expression of SGOC metabolic enzymes, such as PHGDH and SHMT2." (PMID 37147729, 2023). "Phosphoglycerate dehydrogenase (PHGDH), a key enzyme in serine synthesis, is overexpressed in TNBC and basal-like breast cancer, and leads to oncogenesis through disrupting morphogenesis in breast epithelial cells and inducing phenotypic changes." (PMID 37108109, 2023). "Compared to breast cancer cells with low bone metastatic activity, the expression of serine metabolic enzymes (including PHGDH, PSAT1 and PSPH) was increased in breast cancer cells with high bone metastatic activity." (PMID 36998464, 2023). "Phosphoglycerate dehydrogenase (PHGDH), the first rate-limiting enzyme in the serine synthesis pathway, is elevated in ~70% of ER- breast cancers, and PHGDH inhibition showed an anti-proliferative effect." (PMID 37046596, 2023). "For example, expression of phosphoglycerate dehydrogenase (PHGDH), the rate-limiting enzyme in the serine biosynthetic pathway (SBP), is upregulated in breast cancer and melanoma due to genomic amplification of the PHGDH locus." (PMID 36276057, 2022). "Hypoxia-induced expression of PHGDH and SHMT2 was also reported in glioma cell lines and breast cancer stem cells (BCSCs), and knockdown of PHGDH leads to a reduced level of NADPH, elevated ROS, and increased apoptosis under hypoxia." (PMID 35011702, 2022). "PHGDH silencing revealed that PHGDH is required to maintain NADPH levels, mitochondrial redox homeostasis, and for the survival of hypoxic breast cancer cells." (PMID 33801846, 2021). "We found that the promoter regions of PSAT1 and PHGDH contain binding sites for MYC-controlled activating transcription factor 4 (ATF4), which was reported to regulate PSAT1 expression in breast cancer." (PMID 32138178, 2020). "Phosphoglycerate dehydrogenase (PHGDH), the first enzyme of the pathway, is an established oncogene in breast cancer and melanoma, and when overexpressed in MCF10A spheroids, it leads to the formation of disorganized spheroids with filled lumen." (PMID 31930708, 2020). "Among 5 different cancer cell lines, MCF7 (CD44-low breast cancer) and MDA-MB-231 (CD44-high breast cancer) expressed either PHGDH or PSAT1, and PSPH." (PMID 29674746, 2018). "Hypoxia upregulates PHGDH, PSAT1, PSPH, SHMT2, MTHFD2, and MTHFD1L, thus protecting breast cancer stem cells from oxidative damage." (PMID 28649560, 2017). "More recently, it has been found that overexpression of phosphoglycerate dehydrogenase (PHGDH), which is genomically amplified in tumors including breast cancer and melanoma, also produces excess quantities of 2-hydroxyglutarate." (PMID 26950159, 2016). "Our analysis highlighted the relevance of PHGDH and SHMT2 expression as prognostic factor for breast cancer, revealing a substantial ability of these enzymes to predict patient survival outcome." (PMID 25436979, 2014).
breast carcinoma (continued). "Consistent with a reliance of a subset of breast cancers on PHGDH, protein expression was required for growth in a panel of three (BT-20, SK-BR-3, and MCF-7) breast cancer cell lines (including the BT-20 cell line that carries amplification)." (PMID 25574168, 2014). "Also, elevated expression of phosphoglycerate dehydrogenase (PHGDH) and it-mediated diversion of glycolysis into serine biosynthetic pathway have been found to be essential for the proliferation of certain tumor cells, such as breast cancer cells and melanoma cells." (PMID 25120544, 2014). "We examined mRNA from a panel of breast cancer cell lines by real-time RT-PCR and found that compared to MCF10A, PHGDH was expressed at higher levels in the majority, including SUM44 cells, which required insulin for proliferation." (PMID 21437235, 2011). "Here, we show that, mechanistically, NAT10 regulates 3-phosphoglycerate dehydrogenase (PHGDH) and phosphoserine aminotransferase 1 (PSAT1) via its RNA helicase domain to support the proliferation of metastatic breast cancer cells in the serine/glycine-limited brain microenvironment." (PMID 40138393, 2025). "Moreover, Kaplan–Meier plotter database analysis suggested that high PHGDH expression and low D2HGDH expression are both strongly connected with a poor outcome for breast cancer." (PMID 39910592, 2025). "In line with the breast cancer cell line data, we found that treatment of astrocytes with CQ resulted in significantly increased intracellular glycine levels compared to the VHC‐treated controls, providing cellular proof‐of‐concept of PHGDH activation by CQ." (PMID 40616775, 2025). "Additionally, Petri identified four miRNAs in breast cancer cells that directly target the PSAT1 3'UTR (miR-145-5p and miR-424-5p) and the PHGDH 3'UTR (miR-34b-5p and miR-876-5p)." (PMID 38408962, 2024). "PHGDH, the enzyme that catalyzes the first step of the serine biosynthesis pathway, is elevated in 70% of estrogen receptor (ER)-negative breast cancers." (PMID 38408962, 2024). "In contrast, in breast cancer, SIRT2 regulates the reversible acetylation of PHGDH through TIP60 and promotes the binding of PHGDH and RNF5 to induce PHGDH degradation and reducing serine and glycine derived from glucose metabolism via the serine biosynthesis pathway in." (PMID 36993975, 2023). "In addition, HIF-1 and HIF-2 transcription factors can induce the expression of PHGDH, PSAT1, and SHMTs in breast cancer cell lines under hypoxia." (PMID 37147729, 2023). "Another lncRNA PlncRNA-1 could inhibit the proliferation of breast cancer cells by promoting TNF-β protein expression and inhibiting PHGDH protein expression, suggesting that PHGDH functions as an oncogene in breast cancer." (PMID 37127605, 2023). "In breast cancer cells, knockdown of ESRP1 (Epithelial Splicing Regulatory Protein 1) decreased the expression of fatty acid, lipid metabolism targets and oxidoreductases including PHGDH (D-3-phosphoglycerate dehydrogenase)." (PMID 35565242, 2022). "Alternatively, SIRT2 regulates the reversible acetylation of PHGDH through TIP60 and promotes the binding of PHGDH and RNF5 to induce PHGDH degradation, which reduces the serine and glycine levels and disturbs redox homeostasis, thereby inhibiting breast cancer cell proliferation." (PMID 36101744, 2022). "While this limitation of our breast cancer cell line models may simplify our mechanistic understanding of luminal serine auxotrophy, low PSAT1 and low PHGDH would likely result in an even stronger serine auxotrophy phenotype in human breast tumors." (PMID 35045283, 2022). "While PHGDH has traditionally been viewed as the rate-limiting step of serine biosynthesis, our data demonstrate that PSAT1 is limiting for serine biosynthesis in luminal breast cancer cells." (PMID 35045283, 2022).